TRAF6 (TNF receptor associated factor 6)
Diseases named in the same sentence as TRAF6 in open-access papers (continued):
Sharing a sentence is not in itself a finding about the gene and the disease.
pancreatic ductal adenocarcinoma (2 papers, 2025). An infiltrating adenocarcinoma that arises from the epithelial cells of the pancreas. "Similarly, in a study on pancreatic ductal adenocarcinoma (PDAC), in vitro and in vivo experiments confirmed that miR-146a-5p is targeted to the 3′-untranslated region (3′-UTR) of TRAF6." (PMID 40874052, 2025).
papillary carcinoma (2 papers, 2015 to 2020). A malignant epithelial neoplasm characterized by a papillary growth pattern. "The influenced genes by miR-146a include IL-1 receptor-associated kinase 1 (IRAK1), TNF receptor-associated factor 6 (TRAF6), and papillary thyroid carcinoma 1 (PTC1)." (PMID 25983750, 2015). "TRAF6 was reported to be a target of miR-146a in papillary carcinoma and HCC." (PMID 33015045, 2020).
Peri-Implantitis (2 papers, 2017 to 2021). An inflammatory process with loss of supporting bone in the tissues surrounding functioning DENTAL IMPLANTS. "Our data showed that the levels of TLR2, TLR4, IRAK1, and TRAF6 gene expression were in agreement with that in bone loss, suggesting peri-implantitis augmented by glycemic fluctuation were at least partly mediated through the activation of TLR2/4 signaling." (PMID 34401982, 2021). "Thus, down-regulation of miR-146a in peri-implantitis should diminish the inhibition of IRAK1 and TRAF6 and promote activation of the NF-κB and MAPK pathways." (PMID 28864780, 2017).
prostate tumors (2 papers, 2015 to 2018). "Al‐Azayzih observed that stimulation with TGFβ1 induced prostate tumour cell scattering and increased expression of Snail and N‐cadherin through TRAF6‐mediated activation of Rac1/Pak1 pathway." (PMID 29193723, 2018). "TGFβ1 stimulation induces prostate tumour cell scattering and increases the expression levels of Snail and N‐cadherin through the TRAF6‐mediated activation of Rac1/Pak1 pathway." (PMID 29193723, 2018). "In addition, IHC results also showed that TRAF6 levels were strikingly increased in prostate tumors of Ptenpc−/−; Trp53pc−/−; Skp2−/− mice, as compared to that of Ptenpc−/−; Trp53pc−/− mice." (PMID 25596733, 2015).
renal cell carcinoma (2 papers, 2022 to 2023). "Collectively, our results suggested that the TP53INP2 inhibited renal cell carcinoma in a way of regulating the caspase-8/TRAF6 apoptotic signaling pathway." (PMID 35615533, 2022). "Furthermore, miR-146b suppressed the inflammatory response by restraining TRAF6 expression to improve neovascularization in hypercholesterolemic conditions and inhibit the growth of tumors in computed tomography-guided renal cell carcinoma." (PMID 37909731, 2023).
sarcopenia (2 papers, 2020 to 2025). Progressive decline in muscle mass due to aging which results in decreased functional capacity of muscles. "Upregulation of miR-126-5p has demonstrated high diagnostic accuracy for sarcopenia, while miR-146a upregulation contributes to sarcopenia by modulating the IRAK1/TRAF6/NF-κB signaling pathway." (PMID 40678078, 2025). "We found that the protein levels of TLR4, MyD88 and TRAF6 were significantly increased in three sarcopenia muscle samples, while those of the two NF-κB subunits, p50 and p65 were not increased." (PMID 32226296, 2020).
schizophrenia (2 papers, 2020 to 2021). A major psychotic disorder characterized by abnormalities in the perception or expression of reality. "As detailed above, the neuroplastin interaction partners AMPA receptor subunit GluA1 and TRAF6 have also been associated with schizophrenia." (PMID 34680901, 2021). "TRAF6, PRKACA and ACTN1 are all connected to both SRC and PSEN1 and therefore it might be useful to further investigate their interactions in order to better understand the mechanisms that could be involved in Schizophrenia." (PMID 32735660, 2020).
silicosis (2 papers, 2025). Silicosis is a respiratory disease caused by breathing in (inhaling) silica dust. "It’s possible that the targeting of TRAF6 can prevent these detrimental actions and provide a potential therapeutic strategy for LF and related inflammation precipitated by silicosis." (PMID 40504442, 2025). "LF induced by silicosis depends on TRAF6 activation, which regulates downstream TGF-β and NF-κB signalling." (PMID 40504442, 2025). "This suggests that Galunisertib may regulate the autophagy-lysosomal system through the TGF-β/TRAF6/Beclin1 signaling pathway, thereby reducing cell apoptosis and improving fibrosis in silicosis mice." (PMID 41378210, 2025). "To further investigate the role of Galunisertib in inhibiting TGF-β in anti-silicosis fibrosis, we used the GENEMANIA and STRING databases to analyze the interactions between TGF-β, TRAF6, and Beclin1." (PMID 41378210, 2025).
Sjögren's syndrome (2 papers, 2019 to 2020). "Traf6 mRNA levels have been reported to be unperturbed by miR-146a in LPS-stimulated B cells and in the PBMCs of patients with Sjögren's syndrome (in which miR-146a levels are elevated), where Traf6 mRNA levels are, paradoxically, abnormally high." (PMID 30777858, 2019). "In addition, the miR-146a and TRAF6 genes are significantly overexpressed in the PMBCs of patients with Sjögren's syndrome, while the expression of the IRAK1 gene is significantly reduced." (PMID 33294443, 2020).
thymoma (2 papers, 2010 to 2022). A neoplasm arising from the epithelial cells of the thymus. "When bound to the IL-18R, IL-18 induces the formation of an IL-1R-associated kinase (IRAK)/TNF receptor-associated factor-6 (TRAF-6), a multipart structure that has stimulatory activity for nuclear factor κB (NF-κB) in Th1 cells and in EL4/6.1 thymoma cells." (PMID 20565717, 2010).
viral myocarditis (2 papers, 2020 to 2021). Myocarditis that is caused by an infection with a viral agent. "Downregulation of lncRNA-MEG3 leads to the inhibition of inflammation and induces M2 macrophage polarization via the miR-223/TRAF6/NF-κB axis in CVB3-induced viral myocarditis." (PMID 34504807, 2021). "For example, lncRNA MEG3 inhibits M2 macrophage polarization by activating TRAF6 via miRNA-223 downregulation in viral myocarditis." (PMID 34504807, 2021).
ZIKV infection (2 papers, 2022 to 2026). "miR-146a, upregulated after DENV, JEV and ZIKV infections, promotes viral replication by targeting TRAF6 in different cell lines." (PMID 35479613, 2022). "Moreover, ZIKV infection promoted pathogenic T cell infiltration into the CNS by enhancing the expression of chemokines for C-C motif chemokine receptor 2 (CCR2) in astrocytes, which was dependent on tumor necrosis factor receptor-associated factor 6 (TRAF6) signaling." (PMID 41403257, 2026).
/T-cell lymphoma (1 paper, 2014). "Similarly, miR-146a has been shown hypermethylated in NK/T-cell lymphoma, in which miR-146a was shown to target TRAF6 and hence downregulate NF-kB signaling." (PMID 25211095, 2014).
Acute hepatitis (1 paper, 2024). Acute hepatic injury resulting from inflammation typically accompanied by increased serum alanine transaminase activity. "Quercetin also exhibited hepatoprotective effects on acute hepatitis by inhibiting the TRAF6/JNK pathway." (PMID 39211446, 2024).
acute liver failure (1 paper, 2023). Rapid deterioration of liver function causing encephalopathy and coagulopathy. "Thus, inhibition of GSK3β activity could improve cell death levels in acute liver failure by modulating the activity levels of the TRAF6/HDAC3/TAK1 molecular pathway." (PMID 37443080, 2023).
acute lymphoblastic leukemia (1 paper, 2018). Leukemia with an acute onset, characterized by the presence of lymphoblasts in the bone marrow and the peripheral blood. "In addition, apoptosis-resistant B cell-acute lymphoblastic leukemia (B-ALL) cells have aberrantly higher protein level of TRAF5 and TRAF6 in response to irradiation than apoptosis-proficient B-ALL cells." (PMID 30294322, 2018).
AIDS (1 paper, 2015). A syndrome resulting from the acquired deficiency of cellular immunity caused by the human immunodeficiency virus (HIV). "IL-18, CCL2, TRAF6 and IL-12Rβ1 were upregulated in both AIDS and IBD patients compared to controls." (PMID 26475133, 2015).
alcoholic cirrhosis (1 paper, 2017). "The TRAF6-associated risk for SBP was higher in patients with non-alcoholic cirrhosis (adjusted odds ratio 3.04; 95% CI 1.11–8.36; P = 0.031) than in patients with alcoholic cirrhosis (adjusted odds ratio 1.81; 95% CI 1.04–3.17; P = 0.037) according the multivariate logistic regression model." (PMID 28687809, 2017).
anemia (1 paper, 2022). A reduction in the number of red blood cells, the amount of hemoglobin, and/or the volume of packed red blood cells. "Anemia, autoimmune hemolytic, autoinflammation, X-linked TRAF6-mediated NF-kB, and MAP kinase up-regulation in response to TLR7/8 or 9 activations is related mechanisms." (PMID 36004808, 2022).
ankylosing spondylitis (1 paper, 2017). An autoimmune chronic inflammatory disorder characterized by inflammation in the vertebral joints of the spine and sacroiliac joints. "For example, the expression of TRAF-6 in patients with untreated ankylosing spondylitis (AS) was significantly lower than that in a control group, suggesting that the abnormal expression of TRAF-6 may play a role in the pathogenesis of AS." (PMID 28219358, 2017).
antiphospholipid syndrome (1 paper, 2023). A disorder caused by the presence of autoantibodies directed against phospholipids, causing a hypercoaguable state, which may result in blood clots, stroke, heart attack, and in women, significant pregnancy-related complications, including miscarriage and still birth. "This study identified the potential molecular basis of how hucMSC-exos improved antiphospholipid antibody-induced placental injury and highlighted the functional importance of the miR-146a-5p/TRAF6 axis in the progression of obstetric antiphospholipid syndrome." (PMID 37957714, 2023).
arteriosclerosis (1 paper, 2020). A vascular disorder characterized by thickening and hardening of the walls of the arteries. "We measured expression of TLR4, TIRAP, MyD88, TRAF6, p38, NEMO, and IRF5 to test the anti-arteriosclerosis effect of corilagin." (PMID 32849545, 2020).
autism (1 paper, 2024). Persistent deficits in social interaction and communication and interaction as well as a markedly restricted repertoire of activity and interest as well as repetitive patterns of behavior. "Additionally, we demonstrated that MSC-EVs could also alleviate neuroinflammation and autism-like behaviors in BTBR mice via the miR-146a-5p/TRAF6 pathway." (PMID 38741170, 2024).
avian influenza (1 paper, 2020). Infection of domestic and wild fowl and other birds with influenza A virus. "Infected with CK/TX/02/H5N3 avian influenza, reductive miR-146b enhanced the expression of IL-1 receptor associated kinase 1 (IRAK1) and TNF receptor-associated factor 6 (TRAF6)." (PMID 32957919, 2020).
B cell lymphomas (1 paper, 2024). "Moreover, the deletion of TRAF6 in LMP1-driven mouse B cell lymphomas was as effective as the deletion of LMP1 itself in killing the tumor cells." (PMID 38195569, 2024).
bone metabolism disorder (1 paper, 2022). "Hyperoside could rectify bone metabolism disorder in ovariectomized mice, which was related to the inhibition of the TRAF-6 mediated RANKL/RANK/NF-κB signaling pathway and the elevation of the OPG/RANKL ratio." (PMID 36193128, 2022).
Bovine mastitis (1 paper, 2025). INFLAMMATION of the UDDER in cows. "miR-146 has also been studied in bovine mastitis, and it has been shown to play a negative feedback role in the inflammatory process by down-regulating the Toll-Like Receptor 4/TNF Receptor-Associated Factor 6/NF-κB (TLR4/TRAF6/NF-κB) pathway." (PMID 40001538, 2025).
brain inflammation (1 paper, 2021). "MiR-146a was involved in the regulation of brain inflammation by modulating TRAF6/NF-κB or MAPK signaling pathways and could be considered a novel therapeutic agent for treating brain inflammation." (PMID 33967693, 2021).
Cachexia (1 paper, 2012). Severe weight loss, wasting of muscle, loss of appetite, and general debility related to a chronic disease. "In addition to a well-established role of TRAF6 in IL-1R/TLR-mediated signaling pathways during inflammation, a recent report has also implicated TRAF6 in muscle atrophy induced by denervation or cachexia." (PMID 22496778, 2012).
cholera (1 paper, 2017). "The expression of IRAK1 and TRAF6 was only down-regulated in 2 and 3 out of 6 cholera patients at the acute stage of disease although miR-146a and miR-155 were expressed at high levels." (PMID 28319200, 2017).
chronic myeloid leukemia (1 paper, 2024). "In patients with chronic myeloid leukemia (CML), research has revealed grancalcin as a catalyst for K63-linked ULK1 ubiquitination via TRAF6 activation." (PMID 38169510, 2024).
cutaneous squamous cell carcinoma (1 paper, 2018). "Furthermore, we found that TRAF6 plays an essential role in cutaneous squamous cell carcinoma (cSCC) malignant phenotypes, affecting cell growth and migration." (PMID 29463844, 2018).
cystic fibrosis (1 paper, 2019). Autosomal recessive disorder caused by pathogenic variants in the CFTR gene (cystic fibrosis transmembrane conductance regulator), which encodes a chloride and bicarbonate channel expressed in epithelial cells, and follow the diagnosis criteria. "In addition, TRAF6 was demonstrated to be related to the pathways of bacterial infections in cystic fibrosis airways." (PMID 30828372, 2019).
dry eye (1 paper, 2023). "The expression of IRAK1 and TRAF6 was upregulated in the corneas of dry eye model mice and during HCEC inflammation." (PMID 37433841, 2023). "Here, we show that miR-146 negatively regulates the inflammatory IRAK1/TRAF6/NF-κB signaling pathway in dry eye." (PMID 37433841, 2023). "The results showed that the protein expression levels of IRAK1 and TRAF6 were increased in the corneal epithelium and corneal stroma of the DE-group compared with those of the C-group, suggesting that IRAK1 and TRAF6 were involved in corneal inflammation in dry eye model mice." (PMID 37433841, 2023). "The mRNA expression levels of IRAK1, TRAF6 and COX2 in the corneas of dry eye model mice were measured by RT-qPCR." (PMID 37433841, 2023).
dysplasia (1 paper, 2018). A usually neoplastic transformation of the cell, associated with altered architectural tissue patterns. "In the present study, positive TRAF6 staining was mainly located in the cytoplasm of cancer cells and partially in the nucleus, and its expression was significantly increased in SCCHN versus dysplasia and normal mucosa tissues." (PMID 29193723, 2018).
ectodermal dysplasia (1 paper, 2021). "TRAF6 has no established clinical associations; however, ectodermal dysplasia has been noted in a Traf6 -/- mouse model." (PMID 34258050, 2021).
end stage renal disease (1 paper, 2022). "This study postulated that miR146a reduction and TRAF6 upregulation increased the progress of ESRD (end stage renal disease)." (PMID 35444657, 2022).
Flavivirus Infections (1 paper, 2021). Infections with viruses of the genus FLAVIVIRUS, family FLAVIVIRIDAE. "TRAF6 is known to be targeted for degradation during flavivirus infection." (PMID 35127560, 2021).
gastric tumor (1 paper, 2020). "Results showed that TRAF6 presented two bands and was expressed significantly higher in gastric tumor tissues than in normal tissues." (PMID 32724313, 2020). "A total of 18 clinical gastric tumor tissue samples and paired adjacent tissues were obtained to test the expression of TRAF6." (PMID 32724313, 2020).
Hyperinsulinemia (1 paper, 2011). An increased concentration of insulin in the blood. "Then it is possible to suggest that the hyperinsulinemia, present in TFA group, associated to the effect of fatty acids in the intestinal microbial composition modified the intestinal permeability elevating lipopolysaccharides activating the inflammatory cascade, promoting an increase in TRAF-6." (PMID 21266050, 2011).
Hyperkeratosis (1 paper, 2022). Hyperkeratosis is a histopathological term defining a thickened stratum corneum and may be present in many different skin conditions, with many possible overlaps. "p21 staining was enhanced in the outermost layers of the skin from TRAF6[L74H] mice, which could be a consequence of the hyperkeratosis and the cause of skin flaking (see Discussion)." (PMID 35157702, 2022). "Moreover, the outermost skin cells of TRAF6[L74H] mice display enhanced senescence compared to WT mice, which may be driven by hyperkeratosis and lead to the observed flaking of the skin." (PMID 35157702, 2022).
hyperphosphatemia (1 paper, 2021). Abnormally high level of phosphate in the blood. "Lanthanum inhibits TRAF6 expression, and later suppresses NF-κB activation or osteo-/chondrogenic reprogramming within VSMCs in the process of hyperphosphatemia." (PMID 33928079, 2021).
Hypoglycemia (1 paper, 2016). A decreased concentration of glucose in the blood. "Thus, TRAF6-mediated inhibition of CRTC2 may serve as a broad mechanism of septic shock-induced hypoglycemia in multiple tissues, which will need further investigation." (PMID 27990298, 2016).
hypoxic ischemic encephalopathy (1 paper, 2024). "In addition, miR-146b-5p overexpression alleviates neonatal hypoxic ischemic encephalopathy-induced neuronal injury by inhibiting the IRAK1/TRAF6/TAK1/NF-κB pathway." (PMID 38533381, 2024).
infectious colitis (1 paper, 2025). A viral or bacterial infectious process affecting the large intestine. "TRAF6 signaling in dendritic cells enhances immunity by inducing Th1 and Th17 responses, protecting against infectious colitis caused by C. rodentium, and showcasing its crucial role in immune defense mechanisms." (PMID 40136419, 2025).
invasive candidiasis (1 paper, 2015). "MiR-155 miRNA is down-regulated in individuals infected with invasive candidiasis, and cytokine is a target protein that is involved in inflammatory signaling including IRAK1, Traf6 and Myd88." (PMID 26313489, 2015).
Lewis lung carcinoma (1 paper, 2021). "To shed light on the potential effect of TRAF6 on MDSC functions, we constructed murine Lewis lung carcinoma models." (PMID 33717204, 2021).
Listeria infection (1 paper, 2022). "mROS production is triggered by the TLR/TRAF6 pathway in Salmonella infection (or the IFN-γ/STAT1 pathway in Listeria infection), contributing to macrophage clearing of the bacteria." (PMID 35768946, 2022).
lung diseases (1 paper, 2022). "Accordingly, genetically enhancing TRAF6 expression or inhibiting the TRIB3-TRAF6 interaction may represent a novel therapeutic strategy for PF and other fibroproliferative lung diseases." (PMID 35668944, 2022).
lymph node metastasis (1 paper, 2018). "In addition, increased TRAF6 expression is closely associated with lymph node metastasis in patients with SCCHN, and log‐rank analysis showed that high TRAF6 expression in the overall survival of patients with SCCHN represents poor prognosis." (PMID 29193723, 2018).
malignant glioma (1 paper, 2015). A grade III or grade IV glioma arising from the central nervous system. "Our findings suggest miR-146b-5p and TRAF6 as potential therapeutic candidates for malignant gliomas." (PMID 26320176, 2015).
MALT lymphoma (1 paper, 2018). An indolent, extranodal type of non-Hodgkin lymphoma composed of small B-lymphocytes (centrocyte-like cells). "For instance, a missense mutation (H159Y) targeting the cytoplasmic tail of the BAFF-R identified in follicular lymphoma, DLBCL, and less commonly in MALT lymphoma results in the increased recruitment of TRAF2, TRAF3, and TRAF6 to the receptor." (PMID 29587428, 2018). "Constitutive MALT1 protease activity and the capacity of cIAP2-MALT1 to potently activate both the canonical NF-κB1 (via the MALT1-dependent recruitment of TRAF6 and proteolytic inactivation of A20) and non-canonical NF-κB2 pathways (discussed in Section 5) drive the growth of these MALT lymphomas." (PMID 29587428, 2018).